APOBEC3F (apolipoprotein B mRNA editing enzyme catalytic subunit 3F)
Description:
DNA deaminase (cytidine deaminase) which acts as an inhibitor of retrovirus replication and retrotransposon mobility via deaminase-dependent and -independent mechanisms. Exhibits antiviral activity against viruse such as HIV-1 or HIV-2. After the penetration of retroviral nucleocapsids into target cells of infection and the initiation of reverse transcription, it can induce the conversion of cytosine to uracil in the minus-sense single-strand viral DNA, leading to G-to-A hypermutations in the subsequent plus-strand viral DNA. The resultant detrimental levels of mutations in the proviral genome, along with a deamination-independent mechanism that works prior to the proviral integration, together exert efficient antiretroviral effects in infected target cells. Selectively targets single-stranded DNA and does not deaminate double-stranded DNA or single- or double-stranded RNA. Exhibits antiviral activity also against hepatitis B virus (HBV), equine infectious anemia virus (EIAV), xenotropic MuLV-related virus (XMRV) and simian foamy virus (SFV) and may inhibit the mobility of LTR and non-LTR retrotransposons. May also play a role in the epigenetic regulation of gene expression through the process of active DNA demethylation.
Synonyms: A3F; ARP8; BK150C2.4.MRNA; KA6
Tractability: PROTAC: UniProt records ubiquitination sites on it.
Target class: Enzyme; Hydrolase
Gene: Protein-coding gene on chromosome 22 (39,040,604 to 39,055,972, forward strand). Ensembl gene ENSG00000128394.
Subcellular location: Cytoplasm; Cytoplasm, P-body
Subcellular location (Human Protein Atlas): Cytosol; Nucleoplasm
Gene Ontology:
Molecular function: cytidine deaminase activity; identical protein binding; protein binding; RNA binding; zinc ion binding; hydrolase activity
Biological process: antiviral innate immune response; base conversion or substitution editing; clearance of foreign intracellular DNA; DNA cytosine deamination; innate immune response; negative regulation of single stranded viral RNA replication via double stranded DNA intermediate; negative regulation of viral genome replication; negative regulation of viral process; positive regulation of defense response to virus by host; positive regulation of gene expression via chromosomal CpG island demethylation; transposable element silencing; cytidine to uridine editing; defense response to virus
Cellular component: cytoplasm; P-body; ribonucleoprotein complex; apolipoprotein B mRNA editing enzyme complex; nucleus
Genetic constraint (gnomAD): Loss-of-function variants: 36 observed, 46.9 expected, observed/expected ratio (o/e) 0.77, 90% interval 0.59 to 1.01. The upper end of that interval is the gene's LOEUF score, 1.01, which puts it in group 4 of 6, group 1 being the genes least tolerant of losing a copy. Missense variants: 459 observed, 476.04 expected, observed/expected ratio (o/e) 0.96, 90% interval 0.89 to 1.04. Synonymous variants: 192 observed, 176.41 expected, observed/expected ratio (o/e) 1.09, 90% interval 0.97 to 1.23.
Homologues: Orthologues: chimpanzee APOBEC3C (97% identical). Paralogues in human: APOBEC3D (80% identical), APOBEC3B (60% identical), APOBEC3G (50% identical), APOBEC3C (39% identical), APOBEC3A (21% identical), AICDA (20% identical), APOBEC2 (17% identical), APOBEC3H (17% identical), APOBEC1 (15% identical).
Diseases named in the same sentence as APOBEC3F in open-access papers:
APOBEC3F is named in the same sentence as 17 diseases in open-access papers, as found by Europe PMC text mining. Sharing a sentence is not in itself a finding about the gene and the disease. The quoted sentences say what the papers report.
HIV-1 infection (5 papers, 2009 to 2018). The type species of lentivirus and the etiologic agent of acquired immunodeficiency syndrome (AIDS). "Upon HIV-1 infection, A3G and other APOBEC family members, such as APOBEC3F (A3F), are encapsidated into budding virions." (PMID 30574147, 2018). "Consistent with a previous study in CD4+ T cell cultures in vitro, WT HIV-1 infection significantly enhanced the mRNA expression of APOBEC3D, APOBEC3F, and APOBEC3G." (PMID 25330146, 2014). "Although HIV-1 replication is restricted by APOBEC3G/APOBEC3F, TRIM5α, and CD317, none defend HIV-1 infection under natural conditions." (PMID 19344514, 2009).
viral infection (4 papers, 2009 to 2016). "In order to learn if Csy4 affected viral infection through the host defense system, we used RT-qPCR to quantitate the expression of interferon α2, α6, and two host viral restriction factors (APOBEC3F and APOBEC3G)." (PMID 26495836, 2015). "Strikingly, this pattern of human APOBEC3G versus human APOBEC3F expression exactly matched the results obtained upon virus infection." (PMID 19371434, 2009). "Interestingly, we did not observe any human APOBEC3F induction, neither upon viral infection nor with IFNβ stimulation, albeit both promoters carry ISRE elements." (PMID 19371434, 2009).
COVID-19 (3 papers, 2022 to 2024). A disease caused by infection with severe acute respiratory syndrome coronavirus 2. "We found a high expression of APOBEC3A, APOBEC3B, APOBEC3C, APOBEC3D, APOBEC3F, APOBEC3G and APOBEC3H in the classical, intermediate monocytes and NK cells of the COVID-19 patients compared to the healthy or recovered individuals." (PMID 36532041, 2022).
breast carcinoma (1 paper, 2015). "While for other APOBEC members, including APOBEC3D, APOBEC3F, and APOBEC3G, they show DNA hyper-methylation in ER− breast cancer cells when compared to HMEC (P < 0.01, Wilcoxon signed rank test)." (PMID 26682542, 2015). "For other APOBEC family members, they show either extremely low (median log2-transformed RPKM < 0) mRNA levels (including APOBEC3A, APOBEC3H, APOBEC1, APOBEC2, APOBEC4, and AICDA), or no obvious expression differences between ER+ and ER− breast cancers (including APOBEC3D, APOBEC3F, and APOBEC3G)." (PMID 26682542, 2015).
cervical cancer (1 paper, 2020). A primary or metastatic malignant neoplasm involving the cervix. "Therefore, we also integrated the APOBEC family (APOBEC1 APOBEC3A, APOBEC3B, APOBEC3C, APOBEC3D, APOBEC3F, APOBEC3G, and APOBEC3H) mRNA expression of 176 core-set cervical carcinoma samples for multiplatform integrative analyses." (PMID 32211324, 2020).
hepatocellular carcinoma (1 paper, 2020). A malignant tumor that arises from hepatocytes. "APOBEC3F, a member of the cytidine deaminase gene family, is thought to play a role in the cell cycle or growth control, and overexpression of APOBEC3F is also related to poor recurrence-free survival of HBV-related hepatocellular carcinoma." (PMID 33634092, 2020).
immunodeficiency disease (1 paper, 2023). Disease in which there is a deficiency or defect in the mechanisms of immunity, either cellular or humoral. "Apobec3f-related research has focused on immune system diseases, especially immunodeficiency diseases." (PMID 37305390, 2023).
infection (13 papers, 2007 to 2025). The state of being infected such as from the introduction of a foreign agent such as serum, vaccine, antigenic substance or organism. "That said, future studies are now required to evaluate if the down-regulation of CR3 and up-regulation of APOBEC3F are also observed after infection with HIV (or SIVcpz)." (PMID 21187902, 2010). "Surprisingly, APOBEC3G expression during particle production only marginally inhibited HERV-KCON(VSV-G) infection, while APOBEC3F more potently reduced infectivity, reducing titers by about 50-fold." (PMID 17257061, 2007). "No significant change was observed with the expression of ADAR1–3, APOBEC1, APOBEC2, and APOBEC3A 3D, 3G, and 3H, whereas APOBEC3B, and 3C had a significant decrease, and APOBEC3F had a significant increase in A549 cells during the course of infection with H7N9." (PMID 29363430, 2018). "The up-regulation of interferon related genes like APOBEC3G and APOBEC3F, as well as HIV-1 specific cytotoxic T-cell and neutralizing antibody responses might contribute to inhibit viral replication in the acute phase of infection." (PMID 30210504, 2018).
cancer (5 papers, 2015 to 2022). A tumor composed of atypical neoplastic, often pleomorphic cells that invade other tissues. "Furthermore, APOBEC3F and APOBEC3D appear to change in specific cancer environments, such as UCEC; missense mutation is the main form in all mutation events." (PMID 34638749, 2021). "Furthermore, compared with the normal HMECs, the loss of promoter activity at the APOBEC3C, APOBEC3F, and APOBEC3G genes was specifically detected in the ER+ cancer cell." (PMID 26682542, 2015). "Such as APOBEC3F that could be a new treatment target in multiple cancers including COAD." (PMID 36506326, 2022).
tumor (5 papers, 2015 to 2025). "Indeed the expression levels of APOBEC1, APOBEC3B, APOBEC3C and APOBEC3F were found to be significantly higher in both primary and metastatic tumours as compared with normal tissues (P<0.01)." (PMID 26647728, 2015). "High genomic alterations in zesto lesions were inversely correlated with putative tumor suppressor genes (MTUS2, DLGAP3, RTN1, CRLF1, SLC12A5, and PDIA2) and positively correlated with APOBEC mutagenesis (APOBEC3C, APOBEC3G, APOBEC3B, and APOBEC3F) and hypoxia-related gene signatures." (PMID 40319462, 2025).
APOBEC3F also shares sentences with these, for which no sentence is quoted: AIDS (3 papers); glioma (3); colorectal tumors (1); immune system diseases (1); melanoma (1); myeloma (1); Pneumocystis Pneumonia (1).